AHR (aryl hydrocarbon receptor)
Diseases named in the same sentence as AHR in open-access papers (continued):
Sharing a sentence is not in itself a finding about the gene and the disease.
cancer (continued). "We may only speculate about the mechanisms underlying cell-specific induction, which may comprise differential cellular uptake/intake, metabolism of Avitriptan or distinct interactions with the AhR signaling pathway in cancer (LS180), immortalized (MIHA) and normal cells (primary human hepatocytes)." (PMID 32316498, 2020). "Importantly, we provide evidence that AHR might directly regulate these genes, thereby expanding our knowledge on the role of AHR in cancer." (PMID 33260776, 2020). "Thus environmental AHR agonists, and potentially also endogenous, nutritional, and microbiome-derived agonists, may reduce or enhance cancer progression depending on the composition of dietary PUFA, particularly in females." (PMID 32398692, 2020). "Besides, Kyn activating AhR regulated cancer growth and invasion in some malignancies." (PMID 33542896, 2020). "However, activation of AhR may also lead to inhibition of the proliferation of various cancer cells, including liver, prostate and breast cancer and intestinal carcinogenesis in mice." (PMID 31659416, 2020). "While the molecular signal that results in these apparently contradictory results is still unknown, it has been postulated that agonists such as TCDD, 3,3′-diindolylmethane, or Omeprazole induce differential cofactor recruitment by the AHR then those recruited by endogenous ligands in cancer." (PMID 33396563, 2020). "Initial studies on AhR were focused on its role as a chemical sensor signaling molecule responding to environment pollutants, but the range of subjects researched has gradually expanded to include diseases such as cancer and cardiovascular and kidney disorders." (PMID 33415104, 2020). "The findings indicate that the chronic activation of AhR may facilitate cancer development." (PMID 33278884, 2020). "Thus, accumulating evidence indicates that the AHR may be involved in proliferation, cell migration and angiogenesis and may play an important role in cancer progression in a variety of cancer types." (PMID 33203443, 2020). "Furthermore, strategies targeting AHR activity might be beneficial in tackling immunosuppression and malignant properties of cancer cells mediated by Trp catabolites." (PMID 31819194, 2020). "Nonetheless, the activation of AHR by kynurenine (or potential condensation products) has been shown to play a significant role in determining immunological fate and activity under pathological conditions, particularly cancer, where kynurenine levels are significantly increased." (PMID 33348604, 2020). "In addition, AHR was reported to be involved in a multitude of normal physiological function as well as pathological processes such as cell circle regulation, immune response, apoptosis, oxidative stress, cancer, tumorigenesis and CNS metabolism." (PMID 33193710, 2020). "However, the effect of AhR activation on cancer cells remains controversial." (PMID 30872677, 2019). "An ideal P450 inhibitor for use in cancer prevention should not cause AhR activation." (PMID 31022888, 2019). "On the basis of these findings and previous observations showing that AHR plays a role in cancer cell proliferation by interacting with growth factor receptors including EGFR, we explored whether a physical association of GPER with AHR and EGFR may occur in SkBr3 cells upon exposure to 3MC." (PMID 31370872, 2019). "Therefore, the data indicate that the paclitaxel → AR/AhR → ABCG2 axis might form a positive feedback regulatory loop for cancer to develop chemoresistance." (PMID 30986993, 2019). "Additionally, DL-1MT can down-regulates expression of paxillin-family proteins and promotes activation of AHR-driven responses in mesenchymal stromal cells rising a pro-inflammatory signature that may augment the efficacy of cancer immunotherapies." (PMID 30186285, 2018).
cancer (continued). "Studies in a human adenocarcinoma (A549) cell line revealed that DNA binding with the AhR was necessary for the cell cycle and that interaction with an AhR agonist could transform the AhR to its DNA-binding form that stimulated the growth of cancer cells." (PMID 29487603, 2018). "However, the AHR also has been reported to exhibit anti-tumorigenic effects in prostate, stomach liver pancreatic and breast cancers, suggesting that full or partial AHR agonists might be the more appropriate cancer therapeutic." (PMID 29735912, 2018). "However, some studies suggest that AHR inhibition might generate the opposite outcome, calling into question the use of AHR inhibitors for cancer treatment." (PMID 29735912, 2018). "However, beyond the identification of this signal, it has been important for us to define the downstream mechanisms by which 1MT may interact with AHR, in order to better characterize and pharmacologically exploit its cancer immunotherapy-augmenting abilities." (PMID 29190885, 2017). "Furthermore, the demonstration that AHR inhibition significantly reduces expression of these phenotypic and functional cancer stem cell markers encourages the testing of AHR inhibitors, for example, to significantly increase the sensitivity of BCSLCs to conventional chemotherapeutics." (PMID 26984638, 2016). "Notably, AhR also mediates the constitutive IDO expression in cancer cells." (PMID 26881062, 2015). "Taken together, targeting Calpain-10 may help eliminate AhR, thereby preventing cancer progression." (PMID 25226618, 2014). "However, their expression and activity needs further investigation and may ultimately provide further insight into the constitutive AhR signaling observed in advanced staged cancers." (PMID 24755659, 2014). "AhR is historically characterized for its role in mediating the toxicity and adaptive responses to these chemicals, however mounting evidence has established a role for it in ligand-independent physiological processes and pathological conditions, including cancer." (PMID 25068070, 2013). "As a protein related to cancer, AhR maybe a promising target for cancer therapy." (PMID 22592002, 2012). "Thus, the anti-cancer effects of tranilast are AHR dependent." (PMID 21072210, 2010). "For instance, formate derived from Fusobacterium nucleatum can activate aryl hydrocarbon receptor (AhR) signaling, promoting CRC invasion and enhancing cancer stemness." (PMID 41355959, 2026). "AhR stimulates IL-6–dependent STAT3 signaling, which maintains IDO1 expression and thereby immunosuppression in several human cancers." (PMID 40789452, 2025). "In terms of mechanism, DIM can bind to aryl hydrocarbon receptor (AHR), estrogen receptor and androgen receptor (AR) as agonists or antagonists to inhibit proliferation and induce apoptosis in several cancer cell lines." (PMID 40822462, 2025). "Tryptophan metabolism plays a key role in modulating immune response and cancer immunotherapy, with TDO2 and AHR among its crucial mediators." (PMID 40924302, 2025). "Various chemical agents, such as industrial waste and hydrocarbon compounds, can alter the expression or signaling activity of AhR and STAT3 pathways, leading to different types of cancers." (PMID 40141386, 2025). "In healthy PBMCs, co-culture with BxPC-3 cells increased the AHR and CYP1A1 levels, indicating that signals from cancer cells can activate this pathway." (PMID 41357201, 2025). "In contrast, treatment with 7k reduced the expression levels of AhR, AhRR, and IDO-1 in kynurenine-stimulated cancer cells in a dose-dependent manner." (PMID 41155994, 2025).
cancer (continued). "Indole derivatives, produced from tryptophan by gut bacteria, modulate the AHR and PI3K/AKT pathways, influencing cancer cell proliferation and immune responses." (PMID 39948481, 2025). "We further integrated our methylation results with RNA-seq data, and we identified 11 genes, including six related to immune functions (AHR, LRFN5, NTRK2, RSPO2, SAMSN1, and TFEC), and three related to cancer (SLC12A5, SORCS1, and TP63)." (PMID 39795948, 2024). "Further, our study aimed to characterize in GC how AhR and the AhR-related genes cytochrome P450 1A1 (CYP1A1) and P450 1B1 (CYP1B1) affect the mRNA expression of a panel of genes involved in cancer development and progression." (PMID 39200369, 2024). "Studies show that AhR can activate PKA signaling, thereby regulating the activation of cancer stemness." (PMID 39835132, 2024). "Although AhR expression was elevated in NSCLC cells, similar to what was found in other cancer types, it was significantly higher in the cytosol than in the nucleus." (PMID 38680496, 2024). "AhR and CYP450 regulate cancer cell proliferation and development, self-renewal and chemoresistance through inhibition of the PTEN and activation of β-Catenin and Akt pathways." (PMID 39138259, 2024). "Incubation with Fn and formate-induced AhR nuclear translocation increased the invasion and migration of CRC cells, upregulated cancer stemness markers (ALDH1A1, CD44, OCT4, SOX2, CD133, and CD24), enhanced metastatic dissemination, and induced Wnt signaling." (PMID 38448800, 2024). "In addition to TCDD, the prototypical and most potent known environmental ligand in animals and humans, other widespread environmental POP contaminants bind AhR, a basic helix-loop-helix transcription factor, with strong affinities and may chronically activate AhR in cancer progression." (PMID 39200369, 2024). "Mechanisms of this effect may include AhR modulation by urolithin A. The favorable safety profile makes possible the long-term administration of urolithin A. In this regard, clinical studies of long-term therapy with urolithin A for both prevention and add-on therapy of cancer are promising." (PMID 39850551, 2024). "Upon its interaction with aryl hydrocarbon receptor (AhR), KYN plays a tumorigenic role in cancer and immune cells together with TRP depletion in the TME." (PMID 38540735, 2024). "Notably, persistent AHR activation has to be avoided since it may lead to toxicity and cancer." (PMID 39723336, 2024). "The intricate interplay between the AHR and signalling pathways, such as TGF-β, PI3K/AKT/mTOR, NF-κB, FAK/c-Src, and Wnt5a/b-β-catenin, further complicates its role in cancer development." (PMID 39336758, 2024). "The activation of the aryl hydrocarbon receptor (AHR) by kynurenines, which enhances polyamine production, establishes a regulatory loop potentially relevant to cancer’s immunological aspects." (PMID 39457550, 2024). "The influence of the different cancer stages on AhR expression in HNSCC cells was further investigated, and a diminishing trend in AhR expression with an advancing cancer grade was observed." (PMID 38680496, 2024). "AhR expression in cancer cells, localized to the nucleus, was characterized by distinct yellow staining in the DAPI regions of each cancer cell line, as identified via cyan blue Pan-CK staining." (PMID 38680496, 2024). "The activation of transcription factors such as aryl hydrocarbon receptor (AhR) and pregnane X receptor (PXR), which regulate the CYP450 enzymes (CYP1A2, CYP1A2, and CYP3A4), can further induce immunosuppression, cancer, and alter drug toxicity." (PMID 39456567, 2024). "Altogether, these data support previous claims that AhR is detrimental for TNBC19,20,37,44 and suggest a potential role in suppressing immune pathways within the cancer cells." (PMID 38459088, 2024). "Their results indicate that activating AHR in the epithelium enhances barrier integrity in ApcMin mice, contributing to ILA’s overall anti-cancer impact." (PMID 39351241, 2024).
cancer (continued). "IDO1/TDO2 are aberrantly expressed in carcinomas and metabolize TRP into the immune-suppressive metabolite kynurenine (KYN), which can engage the aryl hydrocarbon receptor to drive immunosuppressive transcriptional programs." (PMID 38451784, 2024). "PM2.5 activated AhR, promoted its nuclear translocation and potentiated AhR-mediated transcriptional activation of TMPRSS2 in A549 and H1975 cancer cells." (PMID 37830596, 2023). "Although there have been suggestions that IFN and AhR signalling interact, it has been reported that AhR control of IFN-driven outcomes, notably PD-L1 and IDO activation, can be demonstrated in the context of cancer." (PMID 37238995, 2023). "AhR further interacted with the promoter of TMPRSS2, thereby upregulating TMPRSS2 and IL18 expression to promote cancer progression." (PMID 36975376, 2023). "As it is known that TDO2 regulates the Trp–Kyn–AhR pathway in a similar way to IDO1, this finding would support continued pursuit of this pathway as a therapeutic target in cancer." (PMID 37087488, 2023). "Furthermore, the AhR pathway contributes to the regulation of proliferative and anti-proliferative pathways with immunomodulatory effects, making it a valuable target for the treatment of inflammatory diseases such as MS and in preventing carcinogenesis and cancer treatment." (PMID 37027342, 2023). "The Trp/AHR pathway links the abnormal metabolism of tumor cells to the immunosuppressive TME, and has been a promising target for drug development in cancer immunotherapy." (PMID 37655051, 2023). "TCDD (2,3,7,8-tetrachlorodibenzo-p-dioxin) acted as an AhR agonist and efficiently induced MALAT1 in AsPC-1 and PANC-1 cancer cells." (PMID 37830596, 2023). "To investigate the biological significance of p-AHR in LUAD, we intended to examine several hallmarks of cancer in LUAD." (PMID 37988371, 2023). "Benzo[a]pyrene (BaP), an AhR agonist not only increased nuclear accumulation of AhR, but also transcriptionally downregulated RNF182 in cancer cells." (PMID 37830596, 2023). "Compared to normal lung cell lines, some cancer cell lines, such as the LUAD cell line A549, exhibited enhanced p-AHR levels." (PMID 37988371, 2023). "Formate, a major metabolic product of F. nucleatum, can activate the AhR signaling pathway in CRC, enhancing its cancer stem cell properties and increasing the invasiveness of CRC, ultimately promoting cancer metastasis." (PMID 38023192, 2023). "In cancer patients’ blood, the interplay between kynurenine, IDO, and AHR pathway components can have significant implications." (PMID 37760608, 2023). "Either siRNA silencing or CRISPR-Cas9-based knockout of AHR prevented expression of CYP1A1, but amplified the expression of MMP9, CXCL12 and CXCR4 that contribute to the tumorigenesis and metastasis of the cancer cells." (PMID 37151890, 2023). "Indole, 3-methylindole, indole 3-pyruvate, and indole 3-acetamide were the most potent indoles to elicit nuclear translocation of AhR protein and the binding of the AhR complex to the promoter of CYP1A1 gene in human intestinal LS180 and HT-29 carcinoma cells." (PMID 36757399, 2023). "AhR activation suppresses NK cells and CD8+ t cells cytotoxicity and therefore their capacity to kill cancer cells." (PMID 36613754, 2022). "What is more, kynurenine showed to be a ligand of the human aryl hydrocarbon receptor (AHR), whose activation promotes cancer development via the suppression of the cellular immune response." (PMID 35629952, 2022). "As a member of our risk score model, tryptophan 2,3-dioxygenase 2 (TDO2) catalyzes the commitment step of the KYN metabolic process, which subsequently activates the AhR and contributes to an immunosuppressive TME, and supports the cancer immune escape." (PMID 35626004, 2022). "The AhR is also activated by human epidermal growth factor receptor 2 (HER2) to drive mammosphere formation and cancer stem-like cell maintenance in breast cancers." (PMID 36613754, 2022).
cancer (continued). "The targets of evodiamine include topoisomerases, aryl hydrocarbon receptor (AhR), and transient receptor potential cation channel subfamily V member 1 (TRPV1) in the treatment of different types of cancers." (PMID 35899176, 2022). "Immunostaining revealed a significant reduction in the level of AFB1 adducts in AHR KD cells as opposed to the WT PLC/PRF/5 cells, suggesting a functional link between AHR and the metabolism of AFB1 in hepatocyte-derived cancer cells." (PMID 34373448, 2021). "Nevertheless, in some cancers (COAD and KIRP), inconsistency was observed between AhR expression and activity." (PMID 34290693, 2021). "We found that AHR and CYP1A1 were mainly expressed in cancer cells and immune cells, such as macrophages, and expressed in the nucleus and the cytoplasm." (PMID 34784845, 2021). "AGR2 has been shown to participate in various cancer signalling pathways including Hippo, EGFR, EsR, cyclin D1, Src, c-Myc, survivin, aryl hydrocarbon receptor (AhR) and transforming growth factor-beta (TGF-β)." (PMID 34452625, 2021). "What’s more, a recent study demonstrated that IL4I1 is a major aryl hydrocarbon receptor (AHR)-activating enzyme and endowed cancer cells with the capacity of migration and metastasis." (PMID 34134578, 2021). "In the past decades, the transcription factors (TFs) aryl hydrocarbon receptor (AHR) and hypoxia inducible factor-1α (HIF-1α) have been recognized to strongly impact cancer progression and escape mechanisms." (PMID 34572746, 2021). "The activation of AhR signals induced by Kyn and TDO2 have been observed in lung cancer and demonstrated to be involved in the survival and motility of cancer cells." (PMID 34657603, 2021). "Inhibition of AhR signaling restores proliferation and activation of T cells in the IDO-expressing human cancers." (PMID 34201791, 2021). "The role of AhR in modulating the response to treatment has been more widely studied in the context of cancer immunotherapy and the IDO/TDO/Kyn pathway, linking AhR to the immune response." (PMID 33451095, 2021). "Recent data have shown that different types of human cancer directly produce IL4I1, which generates metabolites that activate the Aryl hydrocarbon receptor (AhR)." (PMID 34068423, 2021). "Actually, an estimated two thirds of cancer patients are linked to environmental factors, such as carcinogenic compounds, and different procarcinogens can be activated or detoxicated through phase I enzymes (mainly cytochromes P450 CYP1A1), which could be mediated by activated AhR." (PMID 33278884, 2020). "Features representative of cancer stem cells show that higher expression of STAT3, AHR, and CCR2 modules distinguishes cancer stem-cell samples from their non–stem cancer cell counterparts." (PMID 32383980, 2020). "In the present study, we identify AHR pathway activity, a downstream component of IDO/TDO-Kyn axis, as a common feature of cancers expressing IDO or TDO and as a driver of T cell dysfunction by promoting a Treg-macrophage suppressive axis in the TME." (PMID 32782249, 2020). "Given the proposed role of the AhR in the regulation of SARS-CoV-2 entry, the ‘cytokine storm’, and anti-viral and anti-cancer defence, factors modulating AhR levels will be important to determine." (PMID 32867244, 2020). "In 2008, Hollingshead group obtained an inflammatory state in MCF-7 breast and ECC-1 endocervical cancer cells, through the administration of IL-1β or phorbol 12-myristate 13-acetate (PMA), in combination with TCDD-induced activation of AhR." (PMID 32722276, 2020). "Gene sets based on aryl hydrocarbon receptor signaling, RORA activates gene expression, and RARRXR pathway identified in our study are related to gene regulation and consequently have a role in cancer." (PMID 32583859, 2020).